MALAT1 (metastasis associated lung adenocarcinoma transcript 1)
Synonyms: miPEP-52; PRO1073; MALAT-1; NCRNA00047; HCN; NEAT2; LINC00047; mascRNA; PRO2853
Gene: Long non-coding RNA gene on chromosome 11 (65,497,606 to 65,508,073, forward strand). Ensembl gene ENSG00000251562.
Gene Ontology:
Biological process: positive regulation of cell motility
Diseases named in the same sentence as MALAT1 in open-access papers:
MALAT1 is named in the same sentence as 464 diseases in open-access papers, as found by Europe PMC text mining. Sharing a sentence is not in itself a finding about the gene and the disease. The quoted sentences say what the papers report.
lung cancer (412 papers, 2007 to 2025). A malignant neoplasm involving the lung. "Beyond lung cancer, Malat1 has also been implicated in breast gynecological and gastrointestinal cancer." (PMID 40861865, 2025). "MALAT1 has been shown to facilitate the proliferation, migration, and invasion of lung cancer cells by modulating the expression of associated genes." (PMID 41394878, 2025). "For example, MALAT1 (Metastasis Associated Lung Adenocarcinoma Transcript 1) is highly expressed in lung cancer and is closely associated with poor prognosis, promoting tumor metastasis by regulating gene transcription and RNA splicing." (PMID 39995658, 2025). "Both in vivo and in vitro studies have shown that MALAT1 is associated with the development of cisplatin-resistant A549 lung cancer cells." (PMID 40352931, 2025). "As the first lncRNA identified, metastasis-associated lung adenocarcinoma transcript 1 (MALAT1) has been recognized as a key regulator of lung cancer metastasis." (PMID 40790019, 2025). "In this context, several studies have linked lncRNAs with VM in lung cancer, for example, the lncRNA MALAT1 (metastasis-associated lung adenocarcinoma transcript 1), which acts as a ceRNA by sponging miR-145-5p, a microRNA with tumor-suppressive properties." (PMID 40277941, 2025). "Within lung cancer pathology, certain lncRNAs, such as MALAT1 and HOTAIR, are significantly associated with the onset and progression of the disease." (PMID 41394878, 2025). "Metastasis-Associated Lung Adenocarcinoma Transcript 1 (MALAT1) is another lncRNA overexpressed in lung cancer." (PMID 40869000, 2025). "MALAT1 was first identified in metastatic lung cancer cells and, like TDP-43, has since been implicated in multiple biological processes, including the regulation of gene expression, alternative splicing, and neuronal synapse formation." (PMID 39837396, 2025). "For instance, the lncRNA MALAT1 (Metastasis‐Associated Lung Adenocarcinoma Transcript 1) is often upregulated in lung cancer, where it promotes tumor growth and metastasis by influencing cell cycle genes." (PMID 39991629, 2025). "One notable lncRNA, MALAT1, has been closely associated with the metastasis of lung cancer and exhibits elevated expression levels in lung cancer tissues and cellular models." (PMID 41394878, 2025). "Several lncRNAs including MALAT1, have been shown to play a role in the development and progression of lung cancer and is associated with poor prognosis in lung cancer patients." (PMID 39912983, 2025). "Previous study have shown that Malat1 expression is associated with circulating MDSCs in lung cancer patients." (PMID 38385073, 2024). "MALAT1, one of the earliest discovered genes linked to lung cancer, is seen as a predictive indicator for lung cancer." (PMID 38270295, 2024). "LncRNA metastasis-associated lung adenocarcinoma transcript 1 (Malat1) is overexpressed and act as an oncogene in most of malignant tumors such as breast cancer, lung cancer, and hepatocellular carcinoma." (PMID 38501046, 2024). "MALAT1 expression also appears to be tightly linked to increased de-differentiation and increased metastatic phenotypes in lung cancers and, furthermore, NEAT1 is found in CSC fractions of LUAD cells." (PMID 39062685, 2024). "The metastasis-associated lung adenocarcinoma transcript 1 (MALAT1) is a highly conserved lncRNA that has been discovered as a prognostic marker for lung cancer metastasis." (PMID 39133718, 2024). "Dysregulated MALAT1 contributes to lung cancer disparities in AAs, suggesting novel diagnostic and therapeutic targets." (PMID 38791954, 2024). "Metastasis-associated lung adenocarcinoma transcript 1 (MALAT1) was initially discovered as a predictor for lung cancer metastasis." (PMID 38521951, 2024).
lung cancer (continued). "Nevertheless, two researches showed that the MALAT1 SNPs (rs619586; A/G) dramatically decreased the risk of lung cancer, and the SNPs (rs3200401; CT) was linked to the susceptibility to NSCLC and lung squamous cell carcinoma (LSCC) in Chinese population." (PMID 38517388, 2024). "MALAT1 is a lncRNA that is highly expressed in lung cancer tissues and has been reported to be associated with tumour cell proliferation and metastasis." (PMID 38918809, 2024). "Additional research is warranted to comprehensively elucidate the precise participation of MALAT-1 in the pathogenesis of lung cancer and to explore its potential utility as both a diagnostic biomarker and a target for therapeutic intervention." (PMID 38511067, 2024). "In this study, by studying a group of lung cancer patients, we aimed to investigate the association between different haplotypes of MALAT1 and the tumor size of in the lymph node of lung cancer and brain metastatic lung cancer." (PMID 36934373, 2023). "Examples of lncRNAs associated with lung cancer BM include the metastasis-associated lung adenocarcinoma transcript 1 (MALAT1 or nuclear enriched abundant transcript 2, NEAT2), which is overexpressed in a variety of tumors, including metastatic NSCLC." (PMID 36765679, 2023). "Compared with the expression of MALAT1 in patients carrying different genotypes, it can be indicated that the decreased MALAT1 level is associated with the decreased size of lung cancer lymph nodes and brain metastatic lung tumors." (PMID 36934373, 2023). "Metastasis-Associated Lung Adenocarcinoma Transcript 1 (MALAT1) is an lncRNA initially associated with lung cancer." (PMID 38002304, 2023). "Metastasis-associated lung adenocarcinoma transcript 1 (MALAT1) was the firstly identified lncRNA that contributed to the metastasis by inducing EMT in lung cancer." (PMID 37311754, 2023). "While the role of lncRNA metastasis-associated lung adenocarcinoma transcript 1 (MALAT1) in lung cancer has been widely analysed, its clinical significance in bone metastasis from lung cancer has been only recently studied." (PMID 37143733, 2023). "MALAT1 was initially found to be associated with lung cancer, but recently MALAT1 has been found to be abnormally expressed in most cancers, working as a decoy for splicing factors leading to splicing malfunctioning." (PMID 35692795, 2022). "The expression of MALAT1 (metastasis-associated lung adenocarcinoma transcript 1) has also been associated with carcinogenesis and is a prognostic marker for lung cancer metastasis." (PMID 35039759, 2022). "Several other lnRNAs such as BC087858, metastasis associated lung adenocarcinoma transcript 1 (MALAT-1) have been implicated in the promotion of EGFR TKIs resistance in lung cancer via regulation of EMT process." (PMID 35209919, 2022). "Metastasis-associated lung adenocarcinoma transcript 1 (MALAT1) was the first lncRNA shown to be implicated in lung cancer metastasis." (PMID 36362424, 2022). "Previously proved, MALAT1 acts crucially in regulating the metastatic phenotype of lung cancer cells, and lung cancer cells deficient of MALAT1 are impaired in terms of their migration and metastasis abilities in xenografted tumors." (PMID 35046387, 2022). "LncRNA MALAT1, an oncogene in lung cancer, is expressed in association with metastasis and survival in lung cancer." (PMID 35280820, 2022). "Malat1 (transcription of lung adenocarcinoma associated with metastasis) had a functional annotation and has been associated with lung cancers." (PMID 35055007, 2022). "Metastasis-associated lung adenocarcinoma transcript 1 (MALAT1) is a highly conserved nuclear lncRNA that was initially identified as a premonitory symbol for lung cancer metastasis." (PMID 35113000, 2022). "A previous study showed that MALAT1 rs619586 polymorphism significantly reduced the risk of lung cancer." (PMID 35928715, 2022).
lung cancer (continued). "MALAT1 (metastasis-associated lung adenocarcinoma transcript 1) was identified as a highly expressed ncRNA in lung cancer." (PMID 36012566, 2022). "MALAT1 is one of the most abundant lncRNAs in normal tissues, and emerging evidence has linked MALAT1 to lung cancer, breast cancer, prostate cancer, and pancreatic cancer." (PMID 36406148, 2022). "Metastasis-associated lung adenocarcinoma transcript 1 (MALAT1) was firstly described in relation to lung cancer aggressiveness." (PMID 35887000, 2022). "Metastasis-associated lung adenocarcinoma transcript 1 (MALAT1) has been first identified as the prognostic marker in lung cancer and has been reported to have a positive association with many other cancers including prostate cancer and hepatic cancer." (PMID 36685879, 2022). "For instance, lncRNA metastasis-associated lung adenocarcinoma transcript 1 (LncRNA MALAT1) acts as a sponge of miR-200a to enhance the proliferation of lung cancer cells and their resistance to gefitinib." (PMID 35014946, 2022). "In our study, we selected rs619586 and rs3200401 in MALAT1 gene to explore their effects on lung cancer susceptibility." (PMID 35928715, 2022). "For instance, the lncRNA metastasis-associated lung adenocarcinoma transcript 1 (MALAT1) was initially discovered in lung cancer, and the overexpression of MALAT1 is associated with a poor prognosis among patients with lung cancer." (PMID 35141159, 2022). "Metastasis-associated lung adenocarcinoma transcript 1 (MALAT1) is a conserved lncRNA implicated in lung metastasis and poor prognosis of lung cancer patients." (PMID 35228564, 2022). "Another LncRNA named metastasis-associated lung adenocarcinoma transcript 1 (MALAT1) is first discovered to prophesy lung cancer metastasis now found to be involved in promoting trophoblast proliferation and invasion." (PMID 35966876, 2022). "For example, MALAT1 is an oncogenic lncRNA implicated in lung cancer, miR-143/145 are downregulated in colorectal cancer and miR-24 acts as a tumour suppressor against gastric cancer." (PMID 36671717, 2022). "LncRNA MALAT1 was first reported in non-small cell lung cancer 23, but few studies have published on its polymorphisms and susceptibility to lung cancer." (PMID 35928715, 2022). "For instance, metastasis-associated lung adenocarcinoma transcript 1 (MALAT1) is one of the first lncRNAs shown to be associated with lung cancer, in which it plays a critical role during metastasis." (PMID 33407724, 2021). "One of the earliest lncRNAs connected to lung cancer is Metastasis Associated in Lung Adenocarcinoma Transcript (MALAT1)." (PMID 33803619, 2021). "Examples of such regulation are the expression of miR-21, which promotes fibrosis and EMT transition and has been implicated in cancer, and the lncRNA Malat1/Neat2, which has been implicated in lung cancer invasion and metastasis." (PMID 34685534, 2021). "For example, MALAT1 is a lncRNA that was one of the first to be associated with lung cancer metastasis, and it can exert pro-cancer effects through the activation of Wnt/β-catenin, EMT, and other signaling pathways." (PMID 34362879, 2021). "In lung cancer, miR-142 inhibited tumor cell proliferation and migration through metastasis associated lung adenocarcinoma transcript 1 (MALAT1)/-catenin signaling." (PMID 33600577, 2021). "For instance, several ncRNAs, such as MALAT1, miR-34, and the let7 family, have now been robustly linked to inducing cellular pathways that maintain the malignant phenotypes of lung cancers." (PMID 33803619, 2021). "Metastasis associated in lung adenocarcinoma transcript (MALAT1) was identified early as a prognostic factor for lung cancer survival." (PMID 33435206, 2021). "Recent studies have shown that long noncoding RNA metastasis-associated lung adenocarcinoma transcript 1 (MALAT-1) has potential application value for clinically diagnosing lung carcinoma." (PMID 34858541, 2021).
lung cancer (continued). "This study aimed to investigate the role of MALAT1 in lung carcinoma progression and the mechanism underlying the role of miR-491-5p in the MALAT1 mediated regulation of UBE2C expression." (PMID 34257576, 2021). "Metastasis-associated lung adenocarcinoma transcript 1 (MALAT1) is considered a key marker of metastasis in lung cancer." (PMID 33425890, 2020). "MALAT1 was one of the first identified lncRNAs associated with human diseases, which was originally described to be associated with metastasis of lung cancer." (PMID 32342982, 2020). "The lncRNA MALAT-1 (metastasis associated lung adenocarcinoma transcript-1) is found to be highly up-regulated in the exosomes derived from serum of lung cancer patients and expression is also correlated with the metastatic stage." (PMID 32641036, 2020). "Early studies indicated MALAT1 actively regulates gene expression, including a set of metastasis-associated genes in lung cancer." (PMID 32920545, 2020). "The association of tumor tissue in such discovery studies is of crucial importance, as we found out that the lung cancer associated lncRNA MALAT1, which is upregulated in tumor tissue was upregulated in healthy plasma." (PMID 32033141, 2020). "High expression of MALAT1 decreased cisplatin sensitivity in lung cancer, and the mechanism is associated with upregulated Multidrug resistance-associated protein 1 (MRP1) and Multi-Drug resistance 1 (MDR1) via STAT3." (PMID 32708561, 2020). "This indicated that MALAT1 can serve not only as a diagnostic marker for EGFR‐mutant lung cancer, but also as an important potential marker for monitoring the efficacy of EGFR‐TKI therapy." (PMID 31691525, 2020). "Studies on MALAT1 have shown this lncRNA to be overexpressed in several cancer tissues, associated with high rates of metastasis, and poor prognosis in lung cancer, breast cancer, colon cancer and esophageal cancer, as well as several other cancer types." (PMID 32646047, 2020). "MALAT1 (metastasis associated in lung adenocarcinoma transcript 1) is another representative oncogenic lncRNA and is highly expressed in the A549 and H1299 lung cancer cell lines, in which miR-124 is downregulated." (PMID 33412752, 2020). "The lncRNA MALAT1 (metastasis-associated lung adenocarcinoma transcript 1), was also found to regulate lung cancer metastatic cascade both in human cell lines and in mice model." (PMID 30719228, 2019). "One of the first cancer-associated lncRNA transcripts, MALAT1 (Metastasis Associated Lung Adenocarcinoma Transcript 1) was discovered in lung cancer." (PMID 30894871, 2019). "Metastasis-associated MALAT1 is a favorable prognostic factor for lung cancer, colorectal cancer, bladder cancer, and glioma." (PMID 32117213, 2019). "One of the earliest lncRNAs to be associated with disease was Malat1 (metastasis-associated lung adenocarcinoma transcript 1), which was shown to associate with metastatic tumors in non–small cell lung cancer patients." (PMID 31616462, 2019). "In recent years, lncRNA MALAT1 has been identified to be associated with tumorigenic conditions, including lung cancer, pancreatic cancer, and cervical cancer." (PMID 31619581, 2019). "While MALAT1 was originally described as a prognostic marker of lung cancer metastasis, emerging evidence has linked this lncRNA to other cancers, such as breast cancer, prostate cancer, pancreatic cancer, glioma, and leukemia." (PMID 30781877, 2019). "Gong et al13 found that SNPs in HOTTIP, H19, and CCAT2 were associated with lung cancer risk, and SNPs in MALAT1, H19, CCAT2, HOTAIR, and ANRIL were related to lung cancer patients’ response to platinum‐based chemotherapy." (PMID 30980423, 2019). "MALAT1 has been found to be upregulated in lung cancer and alters the expression of EMT-associated genes, thus promoting brain metastasis." (PMID 30617305, 2019). "Metastasis associated lung adenocarcinoma transcript-1 (MALAT-1) was firstly identified in lung cancer; it is a lncRNA of over 8 kb." (PMID 31212604, 2019).